NAMPT (nicotinamide phosphoribosyltransferase)
Diseases named in the same sentence as NAMPT in open-access papers (continued):
Sharing a sentence is not in itself a finding about the gene and the disease.
cancer (continued). "NAMPT also performs diverse functions as a secretory protein, which is a novel adipokine involved in inflammation, cell proliferation, apoptosis, cellular migration, and metastasis of cancer cells." (PMID 39643827, 2025). "Notably, NAMPT exacerbates cancer immune evasion mechanisms by influencing immune cell functions and the metabolic environment of tumors." (PMID 40775221, 2025). "It is also likely that there will not be just one treatment for each class, but rather that defining a cancer as either YAPon or YAPoff will direct you towards a subset of drugs - e.g., kinase or YAP/TEAD inhibitors for YAPon cancers and BCL2, XPO1, NAMPT or epigenetic inhibitors for YAPoff cancers." (PMID 40440076, 2025). "Nicotinamide phosphoribosyltransferase (NAMPT) inhibitors represent a clinically applicable drug class that exploits the increased dependence of cancer cells on nicotinamide adenine dinucleotide (NAD+), a coenzyme essential to metabolism and other cellular functions." (PMID 40342733, 2025). "NAMPT is also secreted extracellularly (eNAMPT), where it has been shown to act as a pro-inflammatory cytokine, corresponding to tumor aggressiveness and poor prognosis in certain types of cancer." (PMID 40342733, 2025). "Variable enzyme expression may play a role in tissue-specific sensitivity and resistance to NAMPT inhibition in cancer." (PMID 40342733, 2025). "Similarly, NAMPT inhibitors are found to induce apoptosis in cancer cells, and so are chemotherapeutic agents." (PMID 40085284, 2025). "In summary, our findings reveal that PF403 could serve as a promising lead compound for treating cancer with high NAMPT expression, as NAMPT may play significant regulatory roles in multiple tumor types." (PMID 40486861, 2025). "We speculate that the upregulation of NAMPT and increased glycolysis in established cancers may serve as compensatory mechanisms to restore NAD+ levels in response to Complex I deficiency caused by MT-ND5 mutations." (PMID 40671877, 2025). "Therapeutic strategies aimed at modulating G-CSF/NAMPT signaling could enhance infection control and survival for cancer patients." (PMID 41387444, 2025). "Recognizing that there may be therapeutic benefits of limiting NAD+ in cancer cells, several pharmacological inhibitors of NAMPT have been developed." (PMID 40342733, 2025). "In general, overexpression of the NAMPT/SIRT1 mediated NAD + pathway in cancer and its subsequent suppression by chemotherapy may result in accelerated aging and cognitive deficits." (PMID 40085284, 2025). "Moreover, Nicotinamide phosphoribosyltransferase (NAMPT) is a key enzyme involved in the production of NAD in the salvage pathway required for cancer cell growth and progression." (PMID 40076592, 2025). "Interestingly, Vacor is shown to quickly deplete NAD+ and trigger necrosis in cancer cells by inhibiting NAMPT, NMNAT2, and NAD+-dependent dehydrogenases." (PMID 41009660, 2025). "In the context of cancer biology, NAMPT is often regarded as a potent oncogene." (PMID 39272943, 2024). "Studies have shown that blocking NAD metabolism by inhibiting NAMPT may be a viable therapeutic option in cancer." (PMID 38893173, 2024). "NAMPT inhibitors displayed remarkable anticancer activity in cellular and animal models of cancer." (PMID 38396769, 2024). "Therefore, NAMPT is a biomarker for certain types of cancer, and iNAMPT inhibitors have been tested as a cancer therapy in clinical trials, albeit without success due to toxicity and limited efficacy." (PMID 38898303, 2024). "NAMPT was found to be improperly activated in some types of cancer." (PMID 39337621, 2024). "While several previous studies of NAMPT in cancer have been mainly focused on its upregulated expression level in tumor cells, it has been less clear as to whether NAMPT expression in TME affects CRC progression." (PMID 38308188, 2024). "Initially, NAMPT inhibitors were investigated as NAD+-reducing drugs for the treatment of cancer." (PMID 39766263, 2024).
cancer (continued). "Taken together, our results suggested that the dual-targeting molecule LZFPN-90 could inhibit cancer cell proliferation, arrest the cell cycle in the G2/M phase, and promote apoptosis by inhibiting NAMPT activity." (PMID 38448544, 2024). "Such conjugates show promising activity against cancer-associated carbonic anhydrase IX (CA IX), hypoxia-inducible factor-1 (HIF-1), nicotinamide phosphoribosyltransferase (NAMPT), cyclooxygenase (COX), lipoxygenase (LO), and indoleamine-2,3-dioxygenase-1 (IDO1)." (PMID 39407644, 2024). "The regulatory mechanism of NAMPT in cancer is relatively poorly understood." (PMID 37491379, 2023). "We hypothesized that NAMPT overexpression would be involved in determining cancer cell sensitivity to metformin." (PMID 37583931, 2023). "NAMPT overexpression has been observed in numerous types of cancers, including AML." (PMID 37746249, 2023). "We hypothesize that NAMPT expression may determine the extent to which cancer cells are sensitive to metformin." (PMID 37583931, 2023). "Though in this work, we employ NAMPT inhibition as a strategy to enhance CtBP inhibition, NAMPT has been extensively pursued as a cancer therapeutic target, as certain tumors exhibit absolute dependency on the NAD salvage pathway due to the absence of functional de novo or PH pathways." (PMID 37707363, 2023). "We used mouse models to determine whether NAMPT inhibition could serve as anti-cancer therapy and established two synthetic diets depleted of either niacin (NFD, or a niacin-free diet) or tryptophan (WFD)." (PMID 38092728, 2023). "Besides, researches have suggest that the NAMPT/SIRT pathway is implicated in angiogenesis as well as pro-tumorigenic effects of TANs, which can impact the prognosis of different types of cancers." (PMID 37679744, 2023). "NAMPT promotes cancer progression both through its enzymatic activity, which increases intracellular NAD(H) levels, and by being secreted (extracellular NAMPT, eNAMPT) and binding extracellularly to cell surface receptors such as the C-C chemokine receptor type 5 (CCR5)." (PMID 37037593, 2023). "However, the important contribution of NAMPT to cancer progression warrants the examination of alternative strategies." (PMID 37037593, 2023). "Since NAMPT inhibitors have already undergone clinical trials for other cancers, and based on the pre-clinical results presented here, these molecules could be reconsidered for HGSOC to effectively treat PARPi-resistant patients in a clinical setting." (PMID 36849518, 2023). "NAMPT plays a key role in the development of cancer by promoting EMT in numerous cancers." (PMID 36899911, 2023). "NAMPT expression was significantly higher in cancer tissues than in adjacent tissues." (PMID 37954600, 2023). "To test the first hypothesis, we examined whether certain NAPRT-positive cancer cell lines sensitive to FK866 are subjected to NAM-competitive NAMPT inhibition and NAD+ depletion by FK866." (PMID 37771778, 2023). "The specific cytotoxicity of A4276 sparing NAPRT-positive cell lines in multiple cancer types and normal cells led us to propose three hypotheses regarding the nature of NAMPT inhibitors." (PMID 37771778, 2023). "Previous research has shown that the targeted NAMPT inhibitor FK866 reduces cancer cell viability and triggers cancer cell death; however, whether FK866 affects CCA cell survival has not been addressed before." (PMID 36899911, 2023). "In addition, the expression of NAMPT is strongly correlated with the aggressiveness and stemness of cancer." (PMID 37228120, 2023). "Hence, NAMPT as the most important enzyme in NAD biosynthesis has also become into focus as promising target for specific cancer treatment." (PMID 36900207, 2023). "Interestingly, IDH mutations or the epigenetic effect of 2-HG can decrease the level of NAD+, and inhibiting nicotinamide phosphoribosyltransferase (NAMPT) can induce cytotoxicity in endogenous IDH1/2-mutant cancer cells." (PMID 37108511, 2023).
cancer (continued). "Next, we determined if NAMPT was induced in other cancer types in response to IFNγ." (PMID 36900204, 2023). "NAMPT may prove to be a key factor in determining the resiliency of cancers to cancer therapies, which induce metabolic stress or DNA damage." (PMID 37583931, 2023). "NAMPT was shown to play key roles in modulating inflammation, apoptosis, insulin resistance, and oxidative stress response in different metabolic disorders and cancers." (PMID 36443772, 2022). "The trigger of the epithelial-to-mesenchymal transition by NAMPT was indicated, and the results suggested that NAMPT could induce Snail expression in cancer cells via Akt-GSK-3β-β-catenin axis activation." (PMID 35565188, 2022). "Therefore, NAMPT inhibitors play a key role in energy metabolism in cancer by specifically inhibiting the biosynthesis of NAD+ from niacinamide." (PMID 36497496, 2022). "This reflects the fact that potent and highly active (at least in preclinical models) NAMPT inhibitors, such as FK866 and CHS828, were among the first NAD-lowering agents to be reported and the observation that NAMPT is commonly overexpressed in a variety of human cancers." (PMID 35890147, 2022). "In this review, recent discoveries of NAMPT in cancer studies were focused and integrated." (PMID 35565188, 2022). "Our data indirectly support the concept that sensitizing cancer cells to NAMPT inhibitors in humans may need to combine them with additional inhibitor(s)." (PMID 35396381, 2022). "In cancer cells, reducing NAMPT levels resulted in an increase in ROS and cell death." (PMID 36160449, 2022). "To highlight a possible association between NAMPT expression and BRAF mutations in human cancers, we analyzed the TCGA database showing that BRAF-mutated tumors (MUT, in red) display significantly higher levels of NAMPT, as reported by cumulative distribution function (P = 3.94 × 10–12)." (PMID 35272691, 2022). "It is thus not surprising that NAMPT is overexpressed in cancer cells and that high NAMPT transcript levels are associated with a poor prognosis in several types of cancers." (PMID 35681770, 2022). "Therefore, the ability to predict the response to NAMPT inhibitor treatments by low levels of NAPRT depends on the type of cancer." (PMID 36078035, 2022). "The expression of NAMPT also correlates with the clinical data of cancer patients in some tumours." (PMID 36078035, 2022). "Alternatively, NAphosphoribosyltransferase inhibition may restore anti-cancer activity of NAMPT inhibitors in the presence of gut microbiota and of NAM in the diet." (PMID 35396381, 2022). "The resulting NAD+ production may therefore provide a mechanism to bypass the anti-cancer effects of NAMPT inhibition." (PMID 35396381, 2022). "We recently showed that inhibiting NAPRT could prove useful for sensitizing several cancer cells to NAMPT inhibitors." (PMID 35396381, 2022). "In several types of cancer, it has been described that NAMPT is capable of enriching the CSC population of the tumour through the processes of pluripotency and dedifferentiation, a mechanism by which cells acquire the properties and increase phenotype of tumour stem cells." (PMID 36078035, 2022). "NAMPT is an attractive target in cancer therapy and numerous NAMPT inhibitors have been developed." (PMID 36615364, 2022). "The salvage pathway and its bottleneck enzyme NAMPT is the main NAD+-provider in cancer cells." (PMID 35681770, 2022). "However, the mechanism by which NAMPT regulates immune molecules in cancer cells needs to be determined." (PMID 35515130, 2022). "However, the relationship between NAMPT over-expression in cancer and the activation of oncogenic pathways remains incompletely understood." (PMID 35272691, 2022). "Studies have shown that the NAPRT gene, the second NAD+ production enzyme, is amplified and overexpressed in cancers, and the combined inhibition of NAMPT and NAPRT may help improve drug resistance in tumors." (PMID 35906622, 2022).
cancer (continued). "Given its pleiotropic roles in energy metabolism, promoting DNA repair in response to genomic insults, epithelial to mesenchymal transition, oncogenic signaling, and suppressing the immune surveillance within the tumor milieu, NAMPT remains an attractive target in cancer therapy." (PMID 34068917, 2021). "As a result, NAMPT is considered a promising novel therapeutic target for cancer treatment." (PMID 33912035, 2021). "Our study suggests that NAPRT is involved in differentiation and developmental processes and showed that, beyond its application in cancer therapeutic strategies involving NAMPT, NAPRT may participate in the process of carcinogenesis and tumor progression." (PMID 34946971, 2021). "Dezocine represents a potential candidate treatment for TNBC and perhaps other cancers, and, furthermore, NAMPT may represent a candidate therapeutic target in TNBC." (PMID 33912035, 2021). "Although inhibiting NAMPT has been effective in cancer cells as it attenuates glycolysis and activates autophagy processes, complete inhibition or depletion of NAMPT can cause motor neuron degeneration, motor function deficits, mitochondrial dysfunction, and defective synaptic function in mice." (PMID 33609766, 2021). "Nevertheless, in light of accumulating evidence that substantiated the significance of NAPRT expression as a parallel regulator of NAD metabolism in cancer and as a biomarker for NAMPT inhibitor therapy, the development of NAPRT inhibitors also represents a promising therapeutic approach." (PMID 34068917, 2021). "Among them, the most promising are CD38, CD73 and NAMPT and the disease setting is cancer." (PMID 34421911, 2021). "Many studies have correlated the expression of NAMPT to the clinical outcome of cancer patients." (PMID 33384409, 2021). "Second, the application of NAMPT inhibitors as an anti-cancer agent in humans remains challenging." (PMID 33609766, 2021). "Finally, we summarize the approaches that have been explored to optimize the therapeutic response to NAMPT inhibitors in cancer." (PMID 34068917, 2021). "In the present work, we review the role of NAD+ and NAMPT in the ways that they may influence cancer metabolism, the immune system, stemness, aging, and cancer." (PMID 33384409, 2021). "Accordingly, NAMPT has been regarded as a molecular link between metabolism and cancer." (PMID 33446046, 2021). "Nicotinamide phosphoribosyltransferase (NAMPT), a key enzyme regulating the salvage pathway, has elevated expression in several malignant tumor cells to meet the latter’s large energy requirements, and it has been shown that inhibition of NAMPT blocks glycolysis." (PMID 34926421, 2021). "In order to select the types of cancer that would better respond to NAMPT inhibition, a determination should be made on whether NAPRT is expressed and functional." (PMID 34946971, 2021). "For example, overexpression of NAMPT contributes to cancer pathogenesis and development." (PMID 34445574, 2021). "Cancer cells can develop resistance to NAMPT inhibitors in many ways." (PMID 33384409, 2021). "The oncogene c-MYC was also reported to increase NAMPT expression in cancer cells." (PMID 34095234, 2021). "Hence, low niacin levels, lack of de novo synthesis genes, and selective silencing of NAPRT1 in cancer cells inhibiting the NAMPT pathway create the necessary vulnerability to inhibit cancer cell growth." (PMID 35008323, 2021). "A mitigation strategy for the toxicity has been proposed, where normal cells could be protected by the NAPRT1-dependent NAD salvage pathway which is often inactivated in cancer cells, if nicotinic acid is administered together NAMPT inhibitor." (PMID 33690666, 2021). "The synergistic effect of DNA-damaging reagents and NAMPT inhibitors might help induce apoptosis in cancer cells, as the DNA damage process can consume large amounts of NAD+." (PMID 33609766, 2021). "NAMPT also serves as a biomarker and prognostic indicator in cancer." (PMID 32005247, 2020).
cancer (continued). "There are 8 registered trials for NAMPT inhibitors in cancers in clinicaltrials.gov." (PMID 32111066, 2020). "A role of NAMPT in inflammation is also supported by the number of reports that have shown an effect of NAMPT inhibitors in inflammatory models, but is also directly supported by evidences in cancer biology." (PMID 32477131, 2020). "Furthermore, in various types of cancer cells, NAMPT is found to be up-regulated, although the molecular mechanisms that dictate the salvage pathway choice remain elusive." (PMID 32785052, 2020). "Previous experiments with NAMPT inhibitors suggested that inhibition of the salvage pathway of NAD+ synthesis may have beneficial effects for cancer therapy." (PMID 32392755, 2020). "Lastly, NAMPT might be up-regulated as a resistance pathway operated by cancer cells, and therefore, NAMPT inhibitors could be used together with other oncological drugs to prolong their efficacy or after these drugs in subsequent lines of therapy." (PMID 32477131, 2020). "Likewise, in silico analysis using the Oncomine Cancer Microarray Database revealed the significant upregulation of NAMPT expression levels in CRC tissues compared with those in nontumorous samples in different patient-derived datasets." (PMID 32005247, 2020). "Increased serum concentrations of NAMPT have been linked with diseases such as obesity, non-alcoholic fatty liver disease, diabetes mellitus and in particular, cancers." (PMID 32111066, 2020). "NAMPT knock-down has successfully sensitized cancer cells to increased ROS and cell death." (PMID 32111066, 2020). "Thus, many cancer biologists have explored the strategy of inhibiting NAMPT expression as a means of reducing tumor growth." (PMID 32454935, 2020). "There is a strong rationale to believe that NAMPT inhibitors might render better if in conjunction with other drugs, reducing the metabolic ability, and therefore the defense potential of cancer cells." (PMID 32477131, 2020). "Starting from the observations that (i) the EMT process is associated with the generation and maintenance of cancer stem cells (CSC) and that (ii) the BRAFi-resistant phenotype is accompanied by increased stemness properties, we wondered if NAMPT over-expression induced a stem-like phenotype." (PMID 33419372, 2020). "Serum NAMPT levels have been shown to be increased and often to correlate with cancer prognosis." (PMID 32477131, 2020). "While the effect of NAMPT inhibitors on impairment of energy metabolism in cancer cells has been well-described, more recent insights have uncovered a number of additional targetable cellular processes that are impacted by inhibition of NAMPT." (PMID 32010616, 2019). "Depending on the cancer cell type, NAMPT inhibitors may be able to impair many of these additional functions." (PMID 32010616, 2019). "As a limiting enzyme of the pathway which plays a key role in the maintenance of intracellular NAD+, NAMPT could be an oncogene contributing to the onset, progression and relapse of cancer." (PMID 31119097, 2019). "So, it was supposed that down-regulated miR-154 in cancer cells might be involved in NAMPT up-regulation." (PMID 31675930, 2019). "Regulation of the sirtuins by NAMPT has additionally been reported in other cancer types." (PMID 32010616, 2019). "In addition, cancer types harboring mutations in metabolic pathways, such as isocitrate dehydrogenase (IDH), have been shown to be exquisitely sensitive to loss of NAMPT activity." (PMID 32010616, 2019). "NAMPT has been described as a mediator of cancer cell stemness." (PMID 32010616, 2019). "NAMPT inhibition also affects epithelial-mesenchymal transition (EMT) in cancer cells." (PMID 32010616, 2019). "Thus, they are more dependent on NAD regeneration by the NAMPT pathway, which makes this enzyme a potential target for cancer therapy." (PMID 31357971, 2019). "NAMPT inhibition has also been shown to reverse the ability of cancer cells to dedifferentiate." (PMID 32010616, 2019).